RET (ret proto-oncogene)
Diseases named in the same sentence as RET in open-access papers (continued):
Sharing a sentence is not in itself a finding about the gene and the disease.
adenocarcinoma (71 papers, 2012 to 2026). A common cancer characterized by the presence of malignant glandular cells. "These mutations were primarily detected in adenocarcinoma samples, underscoring their relevance for targeted RET inhibition in this subgroup." (PMID 40563596, 2025). "In patients with advanced NSCLC, EGFR mutations, ALK gene fusion, RET gene fusion, younger age (≤60 years), lymph node N2‐N3 metastasis and the pathological type of adenocarcinoma are all independent risk factors for brain metastasis." (PMID 31769228, 2020). "The most prevalent alterations identified by RNA sequencing included fusions or exon skipping mutations involving therapy-associated genes MET (2.9%), ALK (1.7%), ROS1 (0.9%), and RET (0.7%), all of which were detected at a significantly higher frequency in adenocarcinoma cases." (PMID 39664186, 2024). "Herein, we present a clinical case of a patient with stage IIIA RET fusion-positive adenocarcinoma who received neoadjuvant nivolumab immunotherapy combined with nab-paclitaxel and carboplatin chemotherapy followed by surgery." (PMID 41695350, 2026). "In regards to 11 kinases specifically regulated in AD, siRNA‐mediated gene‐silencing of CDK1, EPHA1, JAK3, RET and ZAP70 caused loss of cell viability in a panel of six human adenocarcinoma cell lines." (PMID 39995112, 2025). "Following the summary of data from 4857 NSCLC patients from previous studies, the prevalence of RET rearrangement proved to be 1.4%, while in the adenocarcinoma group of 3,576 patients 1.8% had RET fusions." (PMID 38953007, 2024). "KRAS, BRAF, STK11/KEAP1, MUTYH/RET, and RBM10/MET-associated modules showed the opposite trend, having significantly higher frequencies of adenocarcinoma cases as genomic alterations increased (P ≤ 0.02)." (PMID 39664186, 2024). "Most prevalent actionable mutations in adenocarcinoma include KRAS, EGFR, ALK, RET, ROS1, BRAF, HER2, MET." (PMID 37301854, 2023). "The rearrangement of the RET gene conditions the activation of cytosolic kinases derived from RET; this rearrangement occurs in 1%–2% of patients with adenocarcinomas." (PMID 36836402, 2023). "GSEA revealed that RET signaling was significantly enriched in SCNPC tumors compared to adenocarcinomas in both UW and SU2C cohorts (p<0.01)." (PMID 33471819, 2021). "Transcriptome analysis of the University of Washington rapid autopsy and SU2C mCRPC datasets revealed upregulated MET and RET expression in SCNPCs relative to adenocarcinomas." (PMID 33471819, 2021). "While the majority of tumors in all three molecular subgroups had adenocarcinoma histology, there was a higher frequency of neuroendocrine histology among RET+ tumors included in this study (RET: 12% vs ALK: 2%, p = 0.025; vs ROS1: 0%, p = 0.010)." (PMID 32183422, 2020). "Chromosomal rearrangements in tumors resulting in RET gene fusions are found in 1–2% of unselected patients with lung adenocarcinoma, and in 6–14% of adenocarcinomas wild-type for other known molecular drivers." (PMID 33553195, 2020). "Further studies are warranted to validate these in a larger patient cohort and identify further markers of interest such as ROS1 and RET rearrangements, other EGFR mutants and in NRAS-, KRAS-mutated adenocarcinomas." (PMID 30889898, 2019). "KRAS, ARID1A, ABL1, ATM, RET, and CDH1 mutations have been detected in the mesonephric adenocarcinomas containing sex cord-like pattern; among these genes, KRAS mutation was the most frequent." (PMID 31739799, 2019). "ROS1- and RET-rearranged adenocarcinomas have a similar histology to ALK-rearranged adenocarcinoma, such as mucinous cribriform pattern or solid signet-ring cell pattern." (PMID 28894699, 2017). "Hematoxylin and -eosin staining revealed an adenocarcinoma with a predominant acinar pattern, and the immunohistochemistry results showed that the RET protein was mainly localized in the cytoplasm." (PMID 27150058, 2016).
adenocarcinoma (continued). "This is consistent with our findings, which show a higher prevalence of RET rearrangements in patients with adenocarcinoma (1.2%, 6/510) compared with those in other histology types (0.2%, 1/427)." (PMID 25881079, 2015). "The recent discovery of a fusion gene that joins the KIF5B and RET oncogene from large-scale sequencing in a subset of NSCLCs have added a novel molecular subtype to the classification scheme for adenocarcinomas." (PMID 23342255, 2012). "GDNF family receptor alpha 1 (GFR-alpha 1) and the receptor tyrosine kinase (RET) are involved in the pathophysiology of both the enteric nervous system and adenocarcinoma cells, suggesting their involvement in the pathology of polypoid GN." (PMID 22978818, 2012). "Key clinical features of patients with RET fusion + NSCLCs are like other fusion-driven diseases: younger age, adenocarcinoma histology, low exposure to tobacco, and with a tendency to spread to the brain (one quarter of the cases with advanced disease at the diagnosis)." (PMID 39199650, 2024). "Interestingly, FOXA2 transcription factor is known to be upregulated in KIF5B-RET fusion adenocarcinomas through RET downstream signaling pathways such as ERK and AKT." (PMID 38132167, 2023). "It is also conceivable that DARPP-32 might contribute to TKI therapy-refractory growth in adenocarcinomas in which additional downstream genetic alterations exist in genes like RET, ALK, BRAF, or KRAS, although such studies are yet to be conducted." (PMID 34675407, 2022). "Interestingly, all RET+ patients had a small primary lesion (<3 cm) with a significantly higher percentage of N2 disease (54.5% for RET+ vs. 22.6% for other adenocarcinoma patients, p = 0.024)." (PMID 34503226, 2021). "RET gene fusions occur more frequently among younger individuals and non-smokers, regardless of the patient’s sex; they are found almost exclusively among patients diagnosed with adenocarcinoma (most often papillary)." (PMID 33921237, 2021). "RET rearrangements were found most frequently, but not exclusively, in adenocarcinomas and occurred in tumors negative for other driver mutations, in agreement with previous reports in predominantly Asian populations." (PMID 25881079, 2015). "Adenocarcinoma cases had a higher prevalence of SNVs, CNVs, and/or fusions/rearrangements in 28 genes including therapy-associated genes such as KRAS (37.5% vs 4.6%), EGFR (17.1% vs 1.3%), BRAF (5.2% vs 1%), ERBB2 (1.8% vs 0.8%), RET (0.9% vs 0.3%), and ROS1 (1.2% vs 0.1%)." (PMID 39664186, 2024). "RET fusions occur in approximately 1–2% of NSCLC cases, predominantly among patients with adenocarcinoma histology, younger age, and limited smoking history." (PMID 41373672, 2025). "Several biomarker-guided therapies have been approved, targeting genes frequently altered in adenocarcinoma, such as EGFR, BRAF, MET, ALK, ROS1, RET and NTRK." (PMID 39199558, 2024). "In some NSCLC patients, mainly adenocarcinoma, molecular alterations in driver genes, like EGFR, KRAS, HER2, ALK, MET, BRAF, RET,ROS1, and NTRK are recognized." (PMID 37346803, 2023). "The majority of the NEPC tumors co-expressed RET and ZBTB7A protein, while the adenocarcinoma tumors primarily expressed only ZBTB7A." (PMID 37065756, 2023). "Adenocarcinomas harbor targetable genomic alterations in ALK, BRAF, EGFR, and ROS1 genes, and novel treatment options such as KRAS Gly12Cys, MET, NTRK, and RET inhibitors, and possibly ERBB2 guided therapies are broadening the clinical repertoire." (PMID 35964518, 2022). "Adenocarcinoma occurs in 98% of RET fusion-positive NSCLC patients, and 70% of RET fusion-positive NSCLC patients are in stage IV at diagnosis." (PMID 36582799, 2022).
adenocarcinoma (continued). "Similar to the UW and SU2C mCRPC cohorts, transcriptome analysis revealed that AR-active adenocarcinoma PDX models had negligible MET and RET transcript expression, whereas 3 of 4 SCNPC PDX models and the NCI-H660 cell line had robust MET and RET expression." (PMID 33471819, 2021). "For instance, adenocarcinoma is generally induced in part to alterations in KRAS, ALK, ROS proto-oncogene 1 (ROS1), Ret proto-oncogene (RET), neurotrophic receptor kinase 1 and neuregulin." (PMID 32316322, 2020). "Although predominantly found in adenocarcinomas, other NSCLC histological subtypes reportedly harboring RET gene fusions include large cell carcinoma, and adenosquamous carcinoma." (PMID 33553195, 2020). "In EGFR and KRAS-wild type adenocarcinomas (EGFRwt/KRASwt), different potential drivers of pathogenesis exist, including ALK, RET, and ROS1 gene fusions, with ALK rearrangements being therapeutically relevant." (PMID 24205279, 2013). "RET rearrangements are more frequently observed in younger, nonsmoking patients with adenocarcinoma histology and often advanced disease." (PMID 39810398, 2025). "ALK, ROS1, and RET rearrangement is typically more common among younger individuals, non-smokers, and light smokers who have been diagnosed with adenocarcinoma." (PMID 39685930, 2024). "In conclusion, our study indicates that patients with NSCLC harboring RET fusions are typically non-smokers diagnosed with adenocarcinoma." (PMID 38317126, 2024). "Of the 86 patients with stage IV NSCLC and RET rearrangement, 65 (75.6%) were nonsmokers and 82 (95.2%) had adenocarcinoma." (PMID 38349001, 2024). "To further interrogate the translational potential of MET and RET expression and cabozantinib treatment in SCNPC, we evaluated two adenocarcinoma LuCaP CRPC PDX models (LuCaP 86.2CR and LuCaP 147CR), 4 SCNPC PDX models (LuCaP 49, 93, 145.1 and 173.1) and the SCNPC NCI-H660 cell line." (PMID 33471819, 2021). "In NSCLC, RET rearrangement is detected in 1–2% of cases, typically adenocarcinoma histology, and without a history of smoking." (PMID 32560187, 2020). "RET rearrangement was found in 17 adenocarcinoma and in one carcinoma not otherwise specified (NOS)." (PMID 28881815, 2017). "VAMP2-NRG1 was reported in a 67-year-old never-smoker woman with adenocarcinoma with no mutation in EGFR, KRAS and BRAF and with no fusion genes involving ALK, ROS1 or RET." (PMID 27626312, 2016). "Previous studies revealed that RET fusions were more common among never-smokers and those with adenocarcinoma histology, and the tumors tended to be small in size, poorly differentiated, and represent N2 disease." (PMID 27563816, 2016). "RET rearrangements have been suggested to be more frequent in Asian patients, in non-smoker and in the adenocarcinoma subgroup." (PMID 25884512, 2015). "Approximately 1.5% of NSCLC cases have RET translocations, typically in younger, non-smoking adenocarcinoma patients." (PMID 25505733, 2014). "Patient characteristics were generally similar between the overall aNSCLC cohort (n=2947) and the RET fusion-positive cohort (n=576), aside from higher proportions of White/Caucasian patients, never smokers, and adenocarcinoma among the RET fusion-positive cohort." (PMID 39980547, 2025). "Other examples of carcinogenic drivers for adenocarcinoma include modifications in protein kinase B (AKT), BRAF, human epidermal growth factor receptor-2 (HER2), phosphatidylinositol-4,5-bisphosphate 3-kinase catalytic subunit alpha (PIK3CA), MET, ROS1, RET, and KRAS." (PMID 35004079, 2022). "Seventeen studies aimed at predicting EGFR status, one aimed at predicting ALK status, three at predicting both EGFR and KRAS status, one at identifying ALK/ROS1/RET fusion-positive versus fusion-negative adenocarcinomas and two at predicting the PD-L1 expression level." (PMID 32486314, 2020).
adenocarcinoma (continued). "In our investigated cohort of triple-negative NSCLCs (EGFR, KRAS, and BRAF mutation negative) the number of cases with either ROS1 or RET fusions were similar to that of ALK-positive cases, supporting the need of multiplexed gene fusion diagnostics in NSCLC and adenocarcinoma specifically." (PMID 28415793, 2017). "The growing number of detected tyrosine kinase fusions in predominantly EGFRwt/KRASwt adenocarcinomas (including ALK, RET, and ROS1) are also becoming increasingly important in the therapeutic setting, as these alterations are/may become targets for specialized molecular agents." (PMID 24205279, 2013). "RET gene fusions are identified in 1%-2% of NSCLC, more frequently in younger, never-smoking patients with adenocarcinoma histology." (PMID 41477385, 2025). "The clinical features of patients with NSCLC harboring RET fusion (RET fusion + NSCLC) include younger age (median age around 60 years), equal prevalence in both sexes, adenocarcinoma histology, poorly differentiated tumors, and no or low exposure to tobacco." (PMID 39199650, 2024). "RET arrangements (RET fusion) have been observed in 1–2% NSCLC, mostly adenocarcinomas, never/light smokers, and younger patients." (PMID 34977873, 2021). "Fusions involving the rearranged during transfection proto-oncogene (RET) occur in 1–2% of NSCLC, and are more commonly seen in patients with minimal to no smoking history and adenocarcinoma histologic subtype, reminiscent of ALK and ROS1 fusions." (PMID 32183422, 2020).
genetic disorder (12 papers, 2014 to 2026). "Paraganglioma-pheochromocytoma syndrome (PGL-PCC) is a distinct genetic disorder with a broad spectrum of hereditary predispositions and should be differentiated from MEN2, a separate genetic disorder caused by mutations in the RET proto-oncogene." (PMID 39591360, 2024). "RET is a well-known PCC/PGL susceptibility gene whose germ-line mutations are associated with hereditary disease." (PMID 27007161, 2016). "After RET screening, we found that 31 (52%) index patients had sporadic disease, and 29 (48%) had hereditary disease." (PMID 30624503, 2018).
endocrinopathies (10 papers, 2017 to 2025). "In any case, the discovery of an unexpected germline pathogenic variant in RET implies meticulous follow-up and timely intervention of associated endocrine abnormalities and may also contribute to a better understanding of the genetic interplay in endocrine disorders." (PMID 39512978, 2024). "With the improved acknowledge of MEN2B, RET mutation testing together with consideration of early features of MEN2B-related non-endocrine disorders is critical to minimize delays in diagnosis and to improve outcomes of MEN2B." (PMID 33071967, 2020). "Of these, 112 patients had apparently sporadic forms of MTC (no family history of MTC, no other endocrine disease), and 52 patients had a positive history of disease, of which 20 were clinically affected by a hereditary disease at diagnosis, and 32 cases were relatives of RET-positive MTC patients." (PMID 41514606, 2025).
benign tumors (7 papers, 2010 to 2023). "Moreover, our study revealed no major RET rearrangements in benign tumors, similar to previous studies." (PMID 37188126, 2023).
infection (7 papers, 2013 to 2024). The state of being infected such as from the introduction of a foreign agent such as serum, vaccine, antigenic substance or organism. "Summary table of published literature on infections occurred after treatment with RET-TKIs." (PMID 39628994, 2024). "Importantly, upon infection of monocytes with Pv-RET, mitochondria colocalize with the phagolysosome containing parasites and produce mROS, suggesting their involvement in parasite killing." (PMID 34311577, 2021). "In animal models, RET ablation impairs gut homeostasis and increases the risks of inflammation or infection in the gut in response to irritants, which could also impact patient ability to remain on RET inhibitor treatment." (PMID 30666215, 2018). "In addition, the antifungal drugs voriconazole and fluconazole used during infections act as CYP3A inhibitors, resulting in increased exposure to RET-TKIs, which may be attributed to recurrent infection events." (PMID 39628994, 2024). "In conclusion, this case describes real-world experiences of using RET-TKIs in patients with RET fusion-positive NSCLC, underscoring the importance of adequate baseline assessment and ongoing monitoring of immune function, infection biomarkers, and chest CT scans to inform future clinical practice." (PMID 39628994, 2024). "Moreover, kinases found to be upregulated by the infection of HIBCPP cells with both N. meningitidis strains in this analysis (downregulated in control cells) include MAPKAPK2, RPS6KB1, RET as well as AKT1 and AKT2, whereas PRKACA activity was upregulated only by MC58siaD." (PMID 37065199, 2023).
endocrine neoplasms (6 papers, 2012 to 2025). "Eighteen patients had RET germline mutation testing due to either young age at presentation or suspicious clinical features of multiple endocrine neoplasm—two patients pre‐operatively and 16 patients post‐operatively—of these, four (9%) patients were positive for a RET germline mutation." (PMID 35412008, 2022). "The somatic RET mutations (exons 10, 11 e 16) have also been described in other endocrine tumors." (PMID 22312249, 2012). "Several studies indicate a correlation among specific RET mutations (genotype) and age of onset, aggressiveness of MTC and the presence or absence of other endocrine neoplasms (phenotype)." (PMID 22312249, 2012). "A germline RET mutation was also found in 78/1264 (6.2%) MTC patients who were diagnosed as sporadic according to their negative familial history and absence of other endocrine neoplasms." (PMID 31510104, 2019).
lung (5 papers, 2017 to 2023). "Overall survival (OS) for Stage IV lung ADC at initial diagnosis were analyzed in patients with BRAF V600E or with undetected mutation (no driver mutation/fusion detected in BRAF, EGFR, KRAS, ALK, ROS1, RET, HER2, or MET genes)." (PMID 31234388, 2019). "Recently, three independent groups reported recurrent genomic rearrangements involving the RET locus in 1-2% of lung AD, predominantly in young patients who were light or non-smokers." (PMID 28460442, 2017).
neurodegenerative disease (5 papers, 2020 to 2023). A disorder of the central nervous system characterized by gradual and progressive loss of neural tissue and neurologic function. "Receptor tyrosine kinases such as EGFR/ErbB and RET are involved in numerous neuronal functions and altered pathways associated with the development of neurodegenerative diseases." (PMID 32967368, 2020). "Finally, these conditional Ret-knockout mice might be useful for investigating the importance of GFL-mediated RET activation in the retina of animal models of other diseases, such as neurodegenerative diseases or genetic disorders." (PMID 34803580, 2021). "Moreover, edaravone shows consistent in-vivo efficacy to activate the GDNF/RET signaling in mouse spinal cord samples, justifying more studies in mouse models of ALS and other neurodegenerative diseases that may benefit from neuroprotection through GDNF/RET activation." (PMID 35012575, 2022).
metabolic disease (3 papers, 2022 to 2023). A congenital disorder (due to inherited enzyme abnormality) or acquired (due to failure of a metabolically important organ) disorder resulting from an abnormal metabolic process. "In addition, there is sufficient evidence that RET plays an important role in other developmental and metabolic disorders." (PMID 36324815, 2022).
congenital kidney malformation (2 papers, 2021 to 2022). "FAT4 has been implicated in human kidney diseases and is involved in normal kidney development through modulating the RET signaling pathway in mouse models." (PMID 36268582, 2022). "Our system offers a unique platform to further investigate how human RET mutations identified in the human CAKUT patients might contribute to congenital kidney malformation." (PMID 34131121, 2021).